SNORD109B (small nucleolar RNA, C/D box 109B)
Synonyms: HBII-438b
Gene: Small nucleolar RNA gene on chromosome 15 (25,278,343 to 25,278,409, forward strand). Ensembl gene ENSG00000239169.
Gene Ontology:
Biological process: RNA processing
Cellular component: nucleolus
Homologues: Paralogues in human: SNORD109A (100% identical).
Diseases named in the same sentence as SNORD109B in open-access papers:
SNORD109B is named in the same sentence as 1 disease in open-access papers, as found by Europe PMC text mining. Sharing a sentence is not in itself a finding about the gene and the disease. The quoted sentences say what the papers report.
infection (1 paper, 2025). The state of being infected such as from the introduction of a foreign agent such as serum, vaccine, antigenic substance or organism. "In contrast to expression changes induced by Delta infection, RT-qPCR validation of Omicron BA.2-infected cells only identified significant regulation of SNORA62, while expression of SNORA46, SNORD97, and SNORD109B was not significantly altered." (PMID 40510596, 2025).